STAT3 (signal transducer and activator of transcription 3)
Diseases named in the same sentence as STAT3 in open-access papers (continued):
Sharing a sentence is not in itself a finding about the gene and the disease.
lung carcinoma (continued). "Further characterization of LINC00152 in regulating STAT3, p38a and other proteins may provide a novel therapeutic target of lung cancer." (PMID 28592840, 2017). "MiR-218 acts as a tumor suppressor in lung cancer via IL-6/STAT3 signaling pathway regulation." (PMID 28830450, 2017). "Additionally, some researchers have demonstrated that multidrug resistance was consistent with STAT3 mRNA overexpression in cisplatin-resistant lung cancer cells." (PMID 28864784, 2017). "Therefore, we conducted this updated meta-analysis to explore the correlation between p-STAT3 overexpression and the overall survival of lung cancer patients, as well as other clinicopathological characteristics." (PMID 28797050, 2017). "Conversely, STAT3 activation confers lung cancer resistant to paclitaxel." (PMID 29072615, 2017). "Importantly, inactivation of STAT3 by LSS-11 repressed the gene expression of MRPs, triggering apoptosis to make resistant lung cancer cells more susceptible to chemotherapy." (PMID 29072615, 2017). "Also, evidence has shown that inhibition of STAT3 with niclosamide in lung cancer cells resulted in increased sensitivity to radiotherapy." (PMID 28877265, 2017). "Additionally, NF-κB inhibition resulted in a decreased induction of IL-6, which is an important STAT3 activator that promotes tumor development and growth in colon cancer and lung cancer." (PMID 27602766, 2016). "To investigate whether STAT3 can, in turn, serve as a mediator of BDNF expression in lung cancer cells, we analyzed the level of phosphorylated STAT3 under serum-deprived conditions by Western blot." (PMID 27456333, 2016). "Notably, the MFGE-8 receptor, which was shown to be preferentially expressed on CSCs in colon and lung cancer cell lines, can induce M2 polarization of macrophages in vitro though STAT3 signaling." (PMID 26980947, 2016). "In lung cancer, constitutively activated STAT3 has been observed in neoplastic cells." (PMID 27602766, 2016). "Rig-G inhibits NF-κB activity by suppressing STAT3 in lung cancer cells." (PMID 27602766, 2016). "Therefore, the molecular mechanisms by which JAK members activate STAT3 in lung cancer remain to be investigated in vitro and in vivo." (PMID 26843613, 2016). "We assessed whether STAT3 is responsible for IL-10 upregulation in lung cancer-conditioned DCs and if it is a target for laricitrin." (PMID 27833081, 2016). "Since Stat3 activation results in overall cancer cell survival and suppression of apoptosis, we thus examined proteins involved in apoptosis and cell cycle progression in lung cancer treated with GA." (PMID 27419630, 2016). "In our case, we have provided evidence that the inhibition of lung cancer growth of the overexpressing Rig-G line was blocked by the transgenic expression of STAT3, indicating that the function of Rig-G in tumor inhibition involves STAT3." (PMID 27602766, 2016). "In contrast, JAK1 has been suggested to activate STAT3 activity in lung cancer cell lines." (PMID 26843613, 2016). "The protein inhibits NF-κB activity by suppressing STAT3 in lung cancer cells." (PMID 27602766, 2016). "Our findings suggest that MAPK, along with STAT3, is important for determining PD-L1 expression, which could be useful for targeted therapies against lung cancers." (PMID 27846317, 2016). "Moreover, the cell survival effect of STAT3 can limit the overall drug response to some lung cancer treatments, such as Erlotinib." (PMID 27445423, 2016). "To study whether BDNF/TrkB signaling regulates the activation of STAT3 in lung cancer cells, we examined the level of phosphorylated STAT3 in cells with or without the Trk inhibitor K252a (100 nM)." (PMID 27456333, 2016). "STAT3 activation is required for TGF-β-induced EMT in lung cancer cells." (PMID 25638155, 2015). "To address this speculation, we used IL-6 to activate STAT3 in lung cancer cells, and found that IL-6 significantly induced phosphorylation of STAT3 and suppressed crizotinib-induced autophagy." (PMID 26384345, 2015).
lung carcinoma (continued). "However, in our effort to find the common signaling pathway involved in crizotinib treatment, the STAT3 pathway was quite outstanding in all the lung cancer cell lines tested." (PMID 26384345, 2015). "Downstream targets of STAT3 enhance invasive cell properties and promote metastasis in lung cancer." (PMID 26314961, 2015). "Its ten hub genes were extracted and confirmed in the literature; seven of them (UBC, SRC, SP1, MYC, STAT3, RB1, and MAPK1) were verified to be associated with lung cancer, while the remaining three genes, JUN, NR3C1, and GRB2, were potentially new candidate lung adenocarcinoma-related genes." (PMID 26402252, 2015). "Furthermore, we have also examined the phosphorylation status after crizotinib treatment in H2228 cells, a confirmed EML4-ALK positive lung cancer cell line, and discovered the phosphorylation level of STAT3 was downregulated as well." (PMID 26384345, 2015). "While Erk1/2-NF-κB pathway was reported to be partially involved in inflammatory factors TGF-β1, TNF-α and IL-6 correlated lung cancer invasion, p38-NF-κB and STAT3-NF-κB pathways were demonstrated to inhibit miR-365 expression and regulate IL-6 repressing miR-98 levels respectively." (PMID 26528698, 2015). "However, the expression of NF-κB, STAT3, and cyclinD1 in the lung cancer tissues was significantly higher than that in the adjacent tissues." (PMID 25823926, 2015). "STAT3-mediated Akt activation resulted EGFR-TKI resistance in lung cancer cells." (PMID 25869210, 2015). "The aim of this study was to determine whether BSN exerts its anti-cancer effects through modulation of the negative regulators of STAT3 signaling pathway in human lung carcinoma cells." (PMID 25788267, 2015). "Recent reports showed constitutive STAT3 activation in lung cancer cell lines and tissues." (PMID 25788267, 2015). "In addition to commercially available STAT3 inhibitors, miR-337-3p, a mature sequence of miR-337, can also inhibit STAT3, sensitizing lung cancer cells to paclitaxel treatment." (PMID 26049416, 2015). "Taken together, these results demonstrated that crizotinib might induce autophagy in targeted lung cancer cells through the inhibition of the STAT3 pathway in a step-wise manner." (PMID 26384345, 2015). "Since our data also revealed the activation of IL-6 inflammatory feedback loop via a STAT3-NF-κB pathway, we speculated that NF-κB may down-regulate miR-124 though repressing HNF4α expression in the metastatic lung cancer cells, needing further study." (PMID 25749519, 2015). "Knockdown of STAT3 conveyed sensitivity to paclitaxel in lung cancer cell lines." (PMID 24699359, 2014). "We asked whether TYK2 evokes STAT3 signaling in lung cancer cells and if SIAH2 can attenuate this process." (PMID 24833526, 2014). "Moreover, we show that SIAH2 reduces TYK2 and the TYK2-dependent activation of STAT3 in lung cancer cells." (PMID 24833526, 2014). "Strong phosphorylation of STAT3 was presented in KIF5B-RET positive lung cancer cells." (PMID 25047660, 2014). "In addition, inhibiting MOR attenuates growth factor-induced phosphorylation/activation of Src, Gab-1, PI3 kinase, Akt and STAT3 with consequent inhibition of human lung cancer proliferation, migration and EMT." (PMID 24662916, 2014). "However, depletion of c-Src by small interfering RNA (siRNA) and sustained inhibition of Src by dasatinib led to JAK-dependent STAT3 activation in lung cancer cells in vitro and in vivo." (PMID 24662938, 2014). "Other results also show that the curcumin significantly suppressed Stat3 phosphorylation in bronchoepithelial cells and lung cancer derived cells, indicative of Stat3 pathway suppression, and finally inhibits the proliferative capacity of bronchoepithelial cells and lung cancer cells." (PMID 25295272, 2014).
lung carcinoma (continued). "Furthermore, we found that KIF5B-RET fusion kinase induced multilevel activation of STAT3 at both Tyr705 and Ser727, and KIF5B-RET-STAT3 signaling related inhibitors repressed the proliferation and tumorigenicity of lung cancer cells significantly." (PMID 25047660, 2014). "However, the direct effect and mechanism of AMPK activation induced by metformin on STAT3 in lung cancer cells still needs further investigation." (PMID 24789104, 2014). "Furthermore, STAT3 can mediate chemoresistance of lung cancer cells and ADC have a higher metastatic potential than SCC, with three out of four ADC subtypes being invasive." (PMID 24833526, 2014). "Taken together, TF may contribute to Stat3 activation-induced tumor metastasis via coagulation in lung cancer cells." (PMID 24086497, 2013). "Combinational targeting on both EGFR and STAT3 may enhance the efficacy of gefitinib or other EGFR TKIs in lung cancer." (PMID 24280348, 2013). "This hypothesis is partly confirmed by the observation that STAT3 is hyperactivated in tyrosine 705 residue in gefitinib-resistant lung cancer cell line derived from wild type A549 cells." (PMID 24280348, 2013). "Here we established a similar STAT3 signaling based luciferase reporter screening system in a human lung cancer cell line A549, which shows constitutive activated STAT3 activity and could be further induced by cytokines like IL-6, EGF, and HGF." (PMID 23704931, 2013). "Thus, the importance of JAK signal transduction in the ability of IL-27 to activate the STAT1 and STAT3 pathways in human lung cancer was studied." (PMID 24274066, 2013). "Based on these observations, we hypothesize that Stat3 downstream genes serve as potential biomarkers for inflammation-induced lung cancer prediction." (PMID 23613996, 2013). "STAT3 decoy has also been shown to inhibit the growth of human lung cancer and glioma." (PMID 24199193, 2013). "The STAT3 activation and the subsequent Akt recovery may be one of the key mechanisms of therapy-induced tumor progression in the lung cancer patients who received EGFR TKI treatment." (PMID 24280348, 2013). "Since the lung cancer lines might express other oncogenes besides Src, we examined the role of Stat3 in the Src-triggered GJIC suppression specifically, using the Src-transduced, SK-LuCi6-Src line." (PMID 23244248, 2012). "We therefore investigated the relevance of STAT3 to the sensitization of lung cancer cells to paclitaxel treatment, by assessing the correlation between paclitaxel response, protein levels of total STAT3 and phospho-STAT3 (pSTAT3) and levels of miR-337-3p in a panel of NSCLC cell lines." (PMID 22723956, 2012). "In a series of biochemical and genetic studies, we clearly showed that Jak2/Stat3 pathway, together with other well characterized IL-6 downstream signal pathways, regulates the autocrine production of IL-6 in lung cancer cells and various drug resistant cancer cells." (PMID 21122157, 2010). "A STAT3 decoy ODN was transfected into A549 lung cancer cell line in vitro by using lipofectamine." (PMID 17683579, 2007). "Our findings highlight that STAT3 may be a good candidate molecular target, and STAT3 decoy ODN may potentially be used as an anti-lung cancer therapeutic small bio-molecule." (PMID 17683579, 2007). "Collectively, we reveal for the first time that Cyclin Y promotes lung cancer radioresistance by binding to Chk1 to activate RRM2/STAT3 signaling, indicating that targeting Cyclin Y may be a promising strategy for enhancing the efficacy of radiotherapy in the treatment of non-small cell lung cancer." (PMID 40083692, 2025).
lung carcinoma (continued). "Thus, inhibiting STAT3 activation may be a new strategy to block CAF protein secretion to reverse osimertinib resistance in lung cancer." (PMID 40703348, 2025). "EGFR-TKIs, including erlotinib and gefitinib, can induce plasma membrane-associated EGFR protein degradation, and the inhibition of STAT3 abrogates erlotinib resistance in lung cancer cells, suggesting that a high level of plasma membrane-associated EGFR may be important in EGFR-TKI resistance." (PMID 39967270, 2024). "Therefore, we hypothesized that RPTOR may promote the brain metastasis of lung cancer through the SPHK2/S1P/STAT3 axis." (PMID 38163890, 2024). "Furthermore, earlier research found that an elevated level of STAT3 phosphorylation may trigger EGFR-TKI resistance in lung cancer patients." (PMID 39264588, 2024). "Furthermore, in vivo and in vitro studies have discovered that lung adenocarcinoma A549 cells induce OCs to secrete the ligand IL-19 for IL-20RB, activating the downstream JAK1/STAT3 signaling pathway, and promoting lung cancer proliferation in the bone microenvironment." (PMID 38571500, 2024). "Therefore, it suggests that miR-526b-3p suppresses STAT3 in CDDP-resistant lung cancer." (PMID 39343796, 2024). "Mesenchymal stem cells could conduce to tumor formation by IL-6/JAK2/STAT3 pathway in lung cancer." (PMID 37716993, 2023). "Collectively, our findings identify the miR-182/IL-8/STAT3 axis as a key regulatory pathway in controlling lung cancer cell-induced osteolytic bone metastasis and suggest a promising therapeutic strategy that targets this regulatory axis to interrupt lung cancer bone metastasis." (PMID 37127752, 2023). "Moreover, silibinin’s pre-treatment reduces the phosphorylation of signal transducer and activator of transcription 1 (STAT1) and signal transducer and activator of transcription 3 (STAT3) induced by cytokines responsible for the proliferation of A549 human lung cancer cells in vitro." (PMID 37915411, 2023). "In addition to a previous study referring to IL-6/STAT3 signaling in the activation of PDL1 expression in lung cancer and M2-type macrophages in hepatocellular carcinoma, here, we provide indirect and direct evidence for such a function of IL-6 in gastric cancer." (PMID 38001573, 2023). "Moreover, the exosome-mediated transfer of miR-193a-3p, miR-210-3p, and miR-5100 (which are derived from hypoxic bone marrow-derived mesenchymal stem cells) has been shown to induce lung cancer cell invasion by modulating signal transducer and activator of transcription 3 (STAT3) signaling pathway." (PMID 36934247, 2023). "Furthermore, erianin also downregulated the protein expression levels of p-STAT3, p-JAK2, MMP-2, MMP-9, COX-2, HIF-1α, and IL-6, indicating that erianin inhibited angiogenesis of lung cancer cells by targeting JAK2/STAT3 pathway and inhibiting IDO-induced angiogenesis." (PMID 37608888, 2023). "Furthermore, p-STAT3 is a marker of poor prognosis and cisplatin resistance in lung cancer." (PMID 36902166, 2023). "The sensitivity to cisplatin in lung cancer was increased after circAKT3 had been knocked down; and therefore, the glucose consumption as well as the lactic acid formation were inhibited via the miR-516b-5p/STAT3 axis, finally, HIF-1α-dependent glycolysis was hindered." (PMID 37599427, 2023). "Furthermore, fibroblast growth factor receptor (FGFR) and IL-6 signaling work in a concerted manner to activate STAT3 following erlotinib treatment in EGFR-mutant lung cancer cells, contributing to the resistance of drug-treated “oncogene-addicted cancer cells”35." (PMID 35228642, 2022). "Therefore, blocking the STAT3/CCL2 signaling pathway may aid in the cessation of lung cancer progression." (PMID 36547079, 2022).
lung carcinoma (continued). "However, there are seven antisense oligonucleotide drugs in clinical trials for cancer with the most advanced being Danvatirsen (AZD9150/IONIS-STAT3-2.5RX) for treatment of lymphoma and lung cancer, which reduces its target, STAT3, lowering IL-6 in the serum and reducing tumour burden." (PMID 35903549, 2022). "Therefore, the STAT3 pathway may represent a promising therapeutic target for the treatment of lung cancer." (PMID 36559280, 2022). "Our results further indicate that Stat3 phosphorylation at Tyr705 and Ser727 have different effects on the phenotype of TNBCs, analogous to their distinct roles in embryonic stem cell self-renewal/lineage commitment and cellular phenotype in pancreatic and lung cancers." (PMID 36017196, 2022). "Moreover, the self-renewal ability of lung cancer stem cells appears to be driven in part by STAT3." (PMID 35406557, 2022). "Signal transducer and activator of transcription factor 3 (STAT3), a key transcription factor, performs a critical role in cancer development, cell survival and chemoresistance, while its inactivation overwhelms drug resistance in numerous cancer types including lung cancer." (PMID 35281907, 2022). "To validate this hypothesis, we analyzed the expression of SMG1 and STAT3 factors by qRT-PCR in a repertoire of human tumor cell lines (29 in total, of different origins, including many lung cancer cell lines), that were selected for their positiveness for IL-6 production." (PMID 36443756, 2022). "In addition, alterations of STAT3 activity using genetic and/or pharmacological methods may be effective in regulating immunosuppression in lung cancer cells, affecting the outcome of cancer immunotherapy." (PMID 36559280, 2022). "STAT3 is capable of modulating miR-21 expression, and the overexpression of miR-21 offsets the effects of STAT3 knockdown, such as reduced proliferation, self-renewal, or migration, suggesting the importance that the STAT3/miR-21 pathway presents in BMs of lung cancer." (PMID 35884446, 2022). "Thus, rhein may be a potential drug and the Stat3/Snail/MMP2/MMP9 pathway may represent novel potential targets for the treatment of lung cancer." (PMID 35178453, 2022). "Like in mESC, overexpression of Smad7 could enhance STAT3 activation in lung carcinoma A549 cells." (PMID 34026434, 2021). "Thus, we reasoned that STAT3/survivin signaling might reveal how AS sensitizes or enhances the effect of DTX in lung cancer cells." (PMID 34885780, 2021). "PDLIM2 downregulation leads to constitutive activation of the transcription factor STAT3, driving AM protumorigenic polarization/activation and differentiation from monocytes attracted from the circulation to suppress cytotoxic T lymphocytes and promote lung cancer." (PMID 33539325, 2021). "In addition, we detected the expression of STAT3 in lung cancer." (PMID 34321456, 2021). "Thus, PD-L1 was a new downstream target of miR-526b-3p/STAT3 mediated cisplatin of lung cancer." (PMID 34321456, 2021). "PLOD3 knockdown could inhibit tumor growth in lung cancer through regulating the PKC-delta signaling pathway, and also in lung cancer, PLOD3 is found to interact with STAT3 immunosuppressive signals, which promotes lung cancer metastasis via dysregulated RAS-MAP kinase pathway." (PMID 34239923, 2021). "Since we found that irradiation specifically suppressed STAT1 and STAT3 phosphorylation in IFNγ-treated A549 cells in this study, we speculated that STAT3 caused radioresistance was mediated by overexpression and activation of mutated EGFR in lung cancer after survived in RT treatment." (PMID 34685495, 2021). "Similarly, STAT3 expression was also increased in lung carcinoma tissue." (PMID 34301920, 2021). "Therefore, BEL's MOA against lung cancer may involve a direct inhibition of STAT3/COX-2 signaling cascades, thereby affecting the caspase-dependent apoptosis pathway and, ultimately, cancer cell damage." (PMID 33299414, 2020).